BPIFA1 (BPI fold containing family A member 1)
Description:
Lipid-binding protein which shows high specificity for the surfactant phospholipid dipalmitoylphosphatidylcholine (DPPC). Plays a role in the innate immune responses of the upper airways. Reduces the surface tension in secretions from airway epithelia and inhibits the formation of biofilm by pathogenic Gram-negative bacteria, such as P.aeruginosa and K.pneumoniae. Negatively regulates proteolytic cleavage of SCNN1G, an event that is required for activation of the epithelial sodium channel (ENaC), and thereby contributes to airway surface liquid homeostasis and proper clearance of mucus. Plays a role in the airway inflammatory response after exposure to irritants. May attract macrophages and neutrophils.
Synonyms: SPLUNC1; LUNX; NASG; PLUNC; SPURT; bA49G10.5
Tractability: Antibody: UniProt places it where antibodies can reach, with high confidence; its Gene Ontology location is reachable by antibodies, with high confidence; UniProt predicts a signal peptide or a membrane-spanning region.
Gene: Protein-coding gene on chromosome 20 (33,235,995 to 33,243,311, forward strand). Ensembl gene ENSG00000198183.
Subcellular location: Secreted
Pathways (Reactome):
Immune System: Antimicrobial peptides
Gene Ontology:
Molecular function: protein binding; lipid binding
Biological process: antibacterial humoral response; antimicrobial humoral immune response mediated by antimicrobial peptide; defense response to virus; immune response in nasopharyngeal-associated lymphoid tissue; innate immune response; multicellular organismal-level water homeostasis; negative regulation of single-species biofilm formation in or on host organism; regulation of sodium ion transmembrane transport; surfactant homeostasis
Cellular component: extracellular region
Genetic constraint (gnomAD): Loss-of-function variants: 24 observed, 24.9 expected, observed/expected ratio (o/e) 0.96, 90% interval 0.7 to 1.36. The upper end of that interval is the gene's LOEUF score, 1.36, which puts it in group 5 of 6, group 1 being the genes least tolerant of losing a copy. Missense variants: 344 observed, 309.08 expected, observed/expected ratio (o/e) 1.11, 90% interval 1.02 to 1.22. Synonymous variants: 139 observed, 135.88 expected, observed/expected ratio (o/e) 1.02, 90% interval 0.89 to 1.18.
Homologues: Orthologues: chimpanzee BPIFA1 (98% identical), macaque BPIFA1 (94% identical), mouse Bpifa1 (73% identical), rat Bpifa1 (72% identical), pig BPIFA1 (70% identical), guinea pig BPIFA1 (69% identical), rabbit BPIFA1 (69% identical), dog BPIFA1 (67% identical), rat Bpifa5 (60% identical), mouse Bpifa5 (59% identical), Caenorhabditis elegans C06E8.5 (12% identical). Paralogues in human: BPIFB1 (27% identical), BPIFB3 (23% identical), BPIFA2 (23% identical), BPIFB4 (21% identical), BPIFA3 (21% identical), BPIFB6 (17% identical), PLTP (16% identical), LBP (15% identical), BPI (13% identical), BPIFB2 (13% identical), CETP (12% identical), BPIFC (11% identical).
Diseases named in the same sentence as BPIFA1 in open-access papers:
BPIFA1 is named in the same sentence as 69 diseases in open-access papers, as found by Europe PMC text mining. Sharing a sentence is not in itself a finding about the gene and the disease. The quoted sentences say what the papers report.
asthma (15 papers, 2010 to 2025). "Several of these DEGs associated with Tet1 loss in AT2 cells (Il33, Areg and Bpifa1, Hspa8 and Lgals3 (also DEGs in ciliated cells)), have been previously linked to asthma." (PMID 35627266, 2022). "A study of BPIFA1 in asthma demonstrated that the CC genotype of the rs750064 polymorphism is associated with reduced BPIFA1 expression in asthmatic nasal epithelial cells, and higher proinflammatory response to IL-13 treatment." (PMID 31931521, 2020). "Normal HBECs exposed to the asthma-associated T-helper 2 cell (Th2) cytokine IL-13 showed similar decreases in BPIFA1 levels." (PMID 28165446, 2017). "Given the higher risk of asthma, more severe symptoms, poorer symptom control, and more frequent exacerbations in obese children, we suspect BPIFA1 could play a certain role in this." (PMID 39609876, 2024). "Strategies that target Orai1 or the BPIFA1 deficiency in asthma may lead to novel therapies to treat this disease." (PMID 28165446, 2017). "Discussions regarding the role of BPIFA1 in asthma have increased in recent years, evaluating its immune modulator function and its potential as a novel therapy." (PMID 38542471, 2024). "Mirroring these decreases, we found that asthma and IL-13 downregulated BPIFA1 mRNA and intracellular protein levels." (PMID 28165446, 2017). "We found that BPIFA1 levels were significantly diminished in sputum derived from asthma patients and that a similar decrease in BPIFA1 levels was observed in apical secretions from both asthmatic and IL-13-exposed HBECs." (PMID 28165446, 2017). "We observed that BPIFA1 protein levels were diminished in sputa from asthma patients." (PMID 28165446, 2017). "Surprisingly, we found that BPIFA1 was secreted basolaterally from normal human bronchial epithelial cultures (HBECs) and that basolateral BPIFA1 secretions were significantly reduced in asthma-derived HBECs." (PMID 28165446, 2017). "Therefore, a better understanding of how BPIFA1 expression is modulated by different categories of β-agonists and other mainstream therapies including glucocorticoids in asthma-derived airway epithelia is needed to develop novel, targeted therapies for treating asthma." (PMID 28165446, 2017). "BPIFA1 is identified as a modifier gene for asthma and its overexpression in non-infectious mouse models increases systemic inflammation." (PMID 39609876, 2024). "We identified a potential five-biomarker panel (BPIFA1, MUC5AC, CAMP, CTSG, and ANXA1) that illustrates the inflammatory activity of asthma in sputum and could improve asthma phenotyping, providing valuable insights into personalized treatment approaches." (PMID 38542471, 2024). "Consistent with our data from the sputum samples, immunoblot analyses revealed significantly decreased levels of BPIFA1 in lysates, basolateral media and apical lavage of HBECs derived from asthma patients compared with non-asthmatic controls." (PMID 28165446, 2017). "To investigate the role of BPIFA1 in asthma pathogenesis, we measured sputum BPIFA1 levels in healthy donors, asthmatic patients, chronic obstructive pulmonary disease patients and atopic individuals without asthma, the latter two cohorts serving as disease controls." (PMID 28165446, 2017). "However, there were no reports, so far, on the roles of BPIFA1, GGH, hsa-miR-30a-3p, hsa-miR-30d-3p, hsa_circ_0001585, hsa_circ_0078031, and hsa_circ_0000552 in asthma." (PMID 34336929, 2021).
lung carcinoma (14 papers, 2008 to 2025). "Among the lung cancer DCB genes, many are associated with surfactant proteins (e.g., SFTA3, SFTPA2, SLC34A2, and BPIFA1), which function to lower surface tension at the air/liquid interface in alveolar cells." (PMID 33883548, 2021). "RNA sequencing revealed a number of genes differentially expressed in lung tumors lacking Akt2 and five of these genes, Actc1, Bpifa1, Mmp2, Ntrk2, and Scgb3a2 have been implicated in human lung cancer." (PMID 26654940, 2016). "One study identified twelve proteins, such as members of the annexin family (annexin A1, A2, A3, A5, A6, A11), along with PR-OM1, MUC1, BPIFA1, CRNN, MUC5B and IQGAP, which showed significant differences between lung cancer patients and healthy individuals." (PMID 40575159, 2025). "For this reason and because our own previous whole transcriptome studies of healthy donor blood samples indicated the absence of BPIFA1 transcripts in healthy blood, we assumed that BPIFA1 would be an ideal marker for lung cancer CTCs." (PMID 34834576, 2021).
cystic fibrosis (12 papers, 2007 to 2025). Autosomal recessive disorder caused by pathogenic variants in the CFTR gene (cystic fibrosis transmembrane conductance regulator), which encodes a chloride and bicarbonate channel expressed in epithelial cells, and follow the diagnosis criteria. "Bpifa1 and Bpifb1 are increased in cystic fibrosis and IPF, which is the most significantly increased secretome-associated protein in UIP." (PMID 37999562, 2023). "Upregulated BPIFA1 expression is known to be sustained under inflammatory conditions, as exemplified in the epithelium of the proximal and distal cystic fibrosis airways, and in in vitro airway cultures of Mycoplasma pneumoniae and Klebsiella pneumoniae." (PMID 35628331, 2022). "We previously demonstrated that genetic variants in the BPIFA1/BPIFB1 region are associated with decreased gene expression and increased lung disease severity in cystic fibrosis." (PMID 31931521, 2020). "Other lower respiratory tract diseases, notably cystic fibrosis, have also demonstrated a correlation between BPIFA1 expression and disease progression." (PMID 30255091, 2018). "Protein levels of both BPIFA1 and BPIFB1 have been shown to be upregulated in subjects with cystic fibrosis, suggesting that these molecules may have a role in the disease." (PMID 31931521, 2020). "The surfactant function of BPIFA1 is demonstrated mainly in cystic fibrosis in the lower airway and is not widely reported in the mucosa of the upper airway." (PMID 30255091, 2018).
nasopharyngeal carcinoma (12 papers, 2009 to 2025). A carcinoma arising from the nasopharyngeal epithelium. "Others, such as the BPIFA1 have been associated with lung disease, as well as nasopharyngeal carcinomas." (PMID 29348853, 2017). "Notably, decreased expression of BPIFA1 and BPIFB1 has been observed in nasopharyngeal carcinoma (NPC) biopsy samples." (PMID 41369347, 2025).
lung disease (11 papers, 2007 to 2025). "We previously identified polymorphisms in the BPIFA1/BPIFB1 region associated with CF lung disease severity." (PMID 31931521, 2020). "Taken together, our data favor BPIFA1 being responsible for the association with CF lung disease severity, since rs1078761 genotype was associated with variation in BPIFA1 protein levels in CF saliva." (PMID 31931521, 2020). "In this study, we build upon our previous work by using an independent CF cohort to replicate the observation that genetic variation in the BPIFA1/BPIFB1 region is associated with CF lung disease severity." (PMID 31931521, 2020). "BPIFB1 levels were not different between genotypes, suggesting that decreased BPIFA1 may be responsible for the association between rs1078761 genotype and CF lung disease severity." (PMID 31931521, 2020). "We evaluated whether the BPIFA1/BPIFB1 associations with lung disease severity replicated in individuals with CF participating in the International CF Gene Modifier Consortium (n = 6,365)." (PMID 31931521, 2020). "Additional studies to characterize the BPIFA1-positive serous cells in human airway epithelium with different pulmonary diseases are ongoing to investigate if the BPIFA1-positive cells are a dynamic reflection of airway epithelial cells’ status of pathophysiological conditions." (PMID 39220634, 2024). "BPIFA1 and BPIFB1 have immunomodulatory activity and genetic variation associated with low levels of these proteins may increase CF lung disease severity." (PMID 31931521, 2020). "To understand how BPIFA1 genotype may modify lung disease severity in patients living with CF, we quantified the BPIFA1 protein levels in the saliva of CF patients who were all clinically stable." (PMID 31931521, 2020). "Amongst top down-regulated isoforms, BPIFB1 (8-fold) and BPIFA1 (6-fold) are members of a family of secreted proteins with unclear biological role and function, but it has been reported that these proteins are differentially expressed in lung diseases." (PMID 28330331, 2016). "Moreover, we provide insight into the causal variant and gene responsible for this robust and replicated association, and we establish that BPIFA1 and BPIFB1 have immunomodulatory functions that may modify lung disease in CF." (PMID 31931521, 2020). "Building on our previous studies of BPIFA1 and BPIFB1 in normal lung and of BPIFA1 in CF tissue, the present study investigates the expression of BPIFB1 and BPIFA1 in lungs from CF patients and in bENaC-Tg mice with CF-like lung disease." (PMID 22767025, 2012). "Furthermore, we investigated mechanisms by which the BPIFA1 and BPIFB1 proteins may modify lung disease in CF." (PMID 31931521, 2020). "Furthermore, our data support a new paradigm by which BPIFA1 and BPIFB1 may contribute to CF lung disease severity, resulting in gene expression changes in CF airway epithelial cells that could influence cell migration through Rho GTPase pathways and also by altering the response to viral infection." (PMID 31931521, 2020).
nasal polyps (6 papers, 2015 to 2023). "Patients with chronic rhinosinusitis with nasal polyps (CRSwNP) were found to have lower levels of BPIFA1 expression, which was associated with bacterial colonization." (PMID 30255091, 2018). "Reduced BPIFA1 expression is associated with bacterial colonization in patients with chronic rhinosinusitis with nasal polyps (CRSwNP)." (PMID 26646664, 2015). "In a recent report, we analyzed patients who underwent sinus surgery for chronic rhinosinusitis with nasal polyps (CRSwNP) and found that reduced BPIFA1 expression was associated with bacterial colonization and negative treatment outcomes in these patients." (PMID 26646664, 2015). "Overall, BPIFA1 has been examined through specific expression in upper airway tracts, including the tongue, tonsil, nasal polyps, adenoid, and middle ear." (PMID 30255091, 2018). "Several reports illustrated a correlation between BPIFA1 expression and middle ear infection, chronic rhinosinusitis with nasal polyps (CRSwNP), and sinusitis." (PMID 30255091, 2018). "Prior to therapy, BPIFA1 expression levels were elevated across all sinonasal regions, particularly in MNT tissue and nasal polyps of severely affected, RIST-negative CRSwNP patients." (PMID 35628331, 2022). "We, thus, aimed to evaluate the transcriptional patterns of ADCAP1, BPIFA1, SOD, and PRDX2 genes across different locations of the nasal cavity, including nasal polyps, bulla ethmoidalis, and middle nasal turbinate tissue of CRSwNP patients." (PMID 35628331, 2022). "The ADCAP1, BPIFA1, and SOD protein levels were previously found to be differentially expressed in nasal polyp and chronic sinusitis tissue of Chinese CRSwNP patients, but their role in the progression or treatment outcome of Caucasian CRswNP endotypes remains unaddressed." (PMID 35628331, 2022). "Similarly, other studies have also reported profound decreases in the expression of BPIFA1 and BPIFB2 in nasal polyps and LTF in nasal tissue of CRSwNP patients." (PMID 33506054, 2021).
chronic obstructive pulmonary disease (5 papers, 2017 to 2025). A chronic and progressive lung disorder characterized by the loss of elasticity of the bronchial tree and the air sacs, destruction of the air sacs wall, thickening of the bronchial wall, and mucous accumulation in the bronchial tree. "For instance, alterations in BPIFA1 expression or dysfunction of serous cells can compromise the protective barrier of the airway epithelium, leading to increased susceptibility to respiratory infections such as pneumonia and chronic obstructive pulmonary disease (COPD)." (PMID 39220634, 2024). "However, this same region in human patients contains human neutrophilic elastase (HNE), which could potentially degrade BPIFA1 in chronic obstructive pulmonary disease (COPD) patients with acute exacerbation of symptoms by nontypeable Haemophilus influenzae infection." (PMID 30255091, 2018).
chronic rhinosinusitis (5 papers, 2014 to 2023). Chronic form of sinusitis. "In a case control study, the level of expression of BPIFA1 was depressed in patients with chronic rhinosinusitis, and the protein was considered to have provided a protective function in the sinus mucosa." (PMID 30255091, 2018). "Some upper airway infectious diseases such as chronic rhinosinusitis and middle ear infection lead to biofilm formation and lower BPIFA1 expression and require avoidable surgeries." (PMID 30255091, 2018).
otitis media (5 papers, 2015 to 2020). Inflammation of the anatomical structures of the middle ear, which is most often caused by an infectious process. "Patients with decreased BPIFA1 expression were also noted to be smokers and to present with allergic rhinitis, conditions which were shown to increase the risk of developing otitis media with related middle ear diseases." (PMID 30255091, 2018). "Middle ear effusion, or otitis media, has been shown to exhibit BPIFA1 gene expression." (PMID 30255091, 2018). "The indirect relationship of otitis media and BPIFA1 may be related to poor eustachian tube function and BPIFA1 expression." (PMID 30255091, 2018).
viral infection (5 papers, 2015 to 2025). "Thus, we show for the first time that club cells producing SCGB1A1 not only can produce mucus after virus infection but also produce increased amounts of BPIFA1." (PMID 25531566, 2015). "However, the modulation of SCGB1A1 and BPIFA1 expression does suggest a role for these factors during the viral infection." (PMID 25531566, 2015).
Mycoplasma pneumonia (4 papers, 2013 to 2022). "For example, higher levels of BPIFA1 have been correlated with the presence of Pseudomonas pneumonia, Klebsiella pneumonia, Mycoplasma pneumonia, and Staphylococcus aureus." (PMID 30255091, 2018). "Neutrophil function was enhanced in the anti-Mycoplasma pneumonia immune response induced by BPIFA1 in chronic lung disease." (PMID 30255091, 2018). "Although Mycoplasma pneumoniae infection increases BPIFA1, IL-13 still decreases BPIFA1 expression and Mycoplasma pneumoniae clearance, suggesting that BPIFA1 serves as a novel host defense protein against Mycoplasma pneumonia." (PMID 30255091, 2018). "It was also reported that BPIFA1 protein binding to bacterial lipopolysaccharide inhibited the growth of Pseudomonas aeruginosa, Klebsiella pneumonia, Mycoplasma pneumonia, and the Gram-positive bacteria Staphylococcus areus by its antimicrobial and surfactant adjusting function." (PMID 30255091, 2018).
bacterial pneumonia (3 papers, 2007 to 2022). Acute infection of the lung parenchyma caused by bacteria (e.g., Streptococcus pneumoniae, Haemophilus influenzae, Chlamydia pneumoniae, Mycoplasma pneumoniae, and Legionella pneumophila). "BPIFB1 was localized in CF lung samples along with BPIFA1, MUC5AC, CD68 and NE and directly compared to histologically normal lung tissues and that of bacterial pneumonia." (PMID 22767025, 2012). "Similarly, Bpifa1 was downregulated in bronchoalveolar lavage fluid (BALF) of C57Bl/6 mice following viral and bacterial pneumonia, and Th1 and Th2 inflammation inhibited its protein expression in vivo." (PMID 36519134, 2022).
lung adenocarcinoma (3 papers, 2021 to 2025). A carcinoma that arises from the lung and is characterized by the presence of malignant glandular epithelial cells. "The remaining 2 lung-specific DCB genes (ROS1, BPIFA1) were also increased in the plasma of patients with lung adenocarcinoma, though it did not rise to the level of statistical significance." (PMID 33883548, 2021).
allergic rhinitis (2 papers, 2007 to 2018). Inflammation of the nasal mucous membranes caused by an IgE-mediated response to external allergens. "Although there are currently no regimens for direct supplementation with BPIFA1, repression of BPIFA1 in patients may still be prevented by controlling or treating the patient's underlying allergic rhinitis or asthma-related disease." (PMID 30255091, 2018). "The BPIFA1 level was significantly lower in patients with persistent allergic rhinitis (AR)." (PMID 30255091, 2018). "Patients presenting with nasal allergies and Th2-predominant upper airway allergic rhinitis had higher IL-13 expression correlated with low BPIFA1 expression and high sinusitis infection rate than patients lacking a background with allergic rhinitis." (PMID 30255091, 2018).